PMP22 (peripheral myelin protein 22)
Diseases named in the same sentence as PMP22 in open-access papers (continued):
Sharing a sentence is not in itself a finding about the gene and the disease.
peripheral neuropathy (continued). "Since peripheral myelin protein 22 (PMP22) is a key component of myelin sheath and has been found mutated and aggregated in several peripheral neuropathies, we predicted that an increase in carbonylation and aggregation of PMP22 may be associated with demyelination in dbdb mice." (PMID 23750273, 2013). "Independently, studies have revealed the altered expression of ABCA1 and dysregulation of cholesterol metabolism in a host of inherited peripheral neuropathies engaging the Peripheral Myelin Protein 22 (PMP22), suggesting shared pathophysiology." (PMID 41750400, 2026). "T118M PMP22 carriers who do present with CMT typically suffer from only mild peripheral neuropathy, similar to PMP22 haploinsufficient (WT/null) HNPP patients." (PMID 36581210, 2023). "In some peripheral neuropathies such as CMT Type 1A, Schwann cell disruption by mutations in peripheral myelin protein 22 (PMP22) or myelin protein zero (MPZ) cause secondary axon degeneration." (PMID 37614471, 2023). "Three of the 4 other peripheral neuropathy-related genes (PMP22, KIF1B, GLA) also have shown to contribute to aberrant mitochondrial dynamics, axonal transport, and/or mitophagy." (PMID 37234784, 2023). "In Charcot–Marie–Tooth disease (CMT), the most common hereditary peripheral neuropathy, the PMP22-duplication was the first variation detected." (PMID 35207700, 2022). "In this study, we used a PMP22-overexpressing mouse model (C22) as a model of inherited peripheral neuropathy such as CMT1A." (PMID 35740439, 2022). "PMP22 overexpression results in a peripheral neuropathy closely resembling the human pathology observed in CMT1A." (PMID 35740439, 2022). "This highlights that SVs, different from PMP22 duplication, can be responsible for peripheral neuropathy and should be searched systematically." (PMID 35207700, 2022). "C3-PMP22 mice, which carry 3–4 copies of the human PMP22 gene, develop a slowly progressive dysmyelinating peripheral neuropathy that is thought to be an appropriate model of CMT1A." (PMID 35501630, 2022). "Such therapeutic strategy faces multiple challenges, in particular the requirement for reaching normal levels of Pmp22, as either too high or too low levels of the protein result in peripheral neuropathy." (PMID 33750896, 2021). "As PMP22 haploinsufficiency and hence under expression is responsible for peripheral neuropathy with liability to pressure palsy (HNPP), the control of the downregulation represents one of the challenges of this gene therapy." (PMID 33883545, 2021). "Recall, deletion of one or both copies of the PMP22 gene causes HNPP, an often painful, compression-induced peripheral neuropathy." (PMID 31455873, 2019). "In our previous study, we demonstrated that in rats Med25 expression correlated with Pmp22 dosage and expression, which is interesting because Pmp22 is a gene involved in demyelinating peripheral neuropathies." (PMID 30039206, 2018). "In relation to peripheral neuropathy, CNVs other than the PMP22 duplication and deletion have been considered rare." (PMID 25648254, 2015). "Using 3D cultures of cells derived from patients with Charcot–Marie–Tooth disease (CMT2A), a recent study generated organoids containing myelinating Schwann cells, enabling the testing of PMP22 inhibitors and the study of cell interactions in peripheral neuropathies." (PMID 40302786, 2025). "While this exact large PMP22 duplication has not been reported before, PMP22 duplications are commonly linked to peripheral neuropathies, such as CMT1A disease." (PMID 39891458, 2024). "Moreover, we report, for the first time, the location of the PMP22 protein in the hippocampus in an animal model (TrJ/+ mice) of the human peripheral neuropathy CMT1E." (PMID 33921657, 2021). "If HSP70.1/3 has a role in assisting the processing of PMP22, one may expect to see myelin-related peripheral neuropathy in HSP70.1/3 knock out animals." (PMID 25694550, 2015).
peripheral neuropathy (continued). "Abnormalities in PMP22 can lead to various peripheral neuropathies." (PMID 21159173, 2010). "Several CMT genes affect the autophagy pathway at different stages, suggesting that autophagy may represent a common pathomechanism in inherited peripheral neuropathies, including CMT1A and CMT1E in which mutations in PMP22 (peripheral myelin protein 22) disrupt the initiation of autophagy." (PMID 32280996, 2021). "As a common peripheral neuropathy that is not classified in the CMT family, we tested for association of T118M PMP22 with CTS." (PMID 36581210, 2023).
tumor (25 papers, 2010 to 2025). "The epithelial membrane proteins (EMPs) are encoded by the peripheral myelin protein 22 kDa (PMP22) gene family, and involved in tumor cell migration, growth, and differentiation." (PMID 37008256, 2023). "This region contains, among others, the gene encoding PMP22 (peripheral myelin protein 22), a protein involved in tumor proliferation, migration and invasion, including via the MAPK (Mitogen-activated protein kinase) pathway." (PMID 35884563, 2022). "Loss of Nf1 activates RUNX1/3 to enable tumor initiation by repressing Pmp22 through alternative promoter usage and other mechanisms to induce protein level expression of PMP22." (PMID 31032403, 2019). "The resulting PMP22-ELOVL5 fusion protein has lost the last 54 amino acids of PMP22, which code for parts of the third and the complete fourth transmembrane domain, possibly resulting in loss of tumor suppressor activity." (PMID 26672768, 2016). "Similar but weaker associations exist between PMP22 gene expression and prognostic values of tumor size and lymph node involvement." (PMID 21159173, 2010). "Proteins linked to cancers (e.g., the tumour suppressor, CDKN2A), CNS disorders (e.g., the myelin constituent, PMP22), and developmental disorders (e.g., skeleton and tooth development protein, SLC10A7) were represented at fCEAA and fEAA extremes." (PMID 39401228, 2024). "EMP3 is a member of the peripheral myelin protein 22-kDa (PMP22) gene family, and it is demonstrated that reintroduction in EMP3-deficient cancer cells inhibits colony formation and tumor growth in xenografts." (PMID 35646656, 2022). "The GAS-3/PMP22 gene family of tumor-associated membrane proteins (TMPs) has multiple biological functions and plays an important role in tumor development." (PMID 36217151, 2022). "PMP22 is significantly expressed in tumor microenvironment macrophages, secretes cell migration factors, and promotes tumor migration." (PMID 36217151, 2022). "Although PMP22 gene deletion has different specific effects on tumor proliferation and demyelination, it also has specific effects on cancer and peripheral tissue cells." (PMID 36217151, 2022). "In our study, we also found anti-apoptotic properties of PMP22, and inhibition of PMP22 strongly suppressed tumor proliferation in vitro and in vivo." (PMID 34421356, 2021). "The knockdown of PMP22 increased both the volume inhibition rate and the tumor weight inhibition rate." (PMID 34421356, 2021). "Several studies have indicated that PMP22 is a potential tumor suppressor 17-22, but other studies report a potential oncogenic function of PMP22 23-31." (PMID 34421356, 2021). "When treated with etoposide, the PMP22 overexpression group showed an increased tumor weight compared to the Ctrl group." (PMID 34421356, 2021). "Some studies have shown that PMP22 is a potential tumor suppressor, and others have indicated that PMP22 has a potential carcinogenic function in tumors." (PMID 34660776, 2021). "Here the enforced PMP22 overexpression significantly inhibited the invasion capacity, in line with the feature of tumor suppressor." (PMID 34689165, 2021). "Several studies indicate that PMP22 is a potential tumor suppressor 8-13, whereas some observations suggest a potential oncogenic function of PMP22 14-22." (PMID 32174796, 2020). "In summary, we show that the SC myelinating gene Pmp22 serves as a tumor suppressor to contribute to neurofibromagenesis." (PMID 31032403, 2019). "A member of the growth arrest specifϊc-3/peripheral myelin protein-22 (GAS3/PMP22) family of tetraspan proteins, overexpression of EMP2 is associated with tumor progression as well as poor patient survival." (PMID 22585360, 2013).
tumor (continued). "Statistical analysis revealed a significant inverse correlation of EMP2 and PMP22 expression in tumor tissues with differentiation grade (p = 0.005 and p = 0.019, respectively)." (PMID 21159173, 2010). "The proportion of variation in time to tumor-specific death explained by PMP22 expression and all covariates was 22.3%." (PMID 21159173, 2010). "The differential expression of PMP22 mRNA in different tumors indicates that to better understand its role in the tumor, PMP22 protein should be more thoroughly studied, which might involve the post-transcriptional regulation of the PMP22 gene." (PMID 36217151, 2022). "Additionally, we observed that knockdown of PMP22 reduced tumor weight, and this inhibition was more obvious after etoposide treatment." (PMID 34421356, 2021). "Finally, overexpression of miR-139-5p significantly inhibited tumor growth in nude mice xenografted with GC cells.and the miR-139-5p levels were inversely correlated with PMP22 expression in nude mice tumor." (PMID 32174796, 2020). "In our study, miR-139-5p and PMP22 knockdown both suppress the NF-κB signaling pathway, and PMP22 overexpression rescued the miR-139-5p-induced NF-κB reporter activity, suggesting that PMP22 may enhance tumor proliferation through the NF-κB signaling pathway." (PMID 32174796, 2020). "To determine whether these regulators are related to Pmp22 expression in our system, we searched the gene expression change on the Runx1fl/fl;Runx3fl/fl;Nf1fl/fl;DhhCre versus Nf1fl/fl;DhhCre tumor RNA-seq data." (PMID 31032403, 2019). "Notably, Pmp22 mRNA relative expression fold change was lower than bulk tumor RNA-seq analysis (2.3×)." (PMID 31032403, 2019). "The varied expression of PMP22 in different tumor types indicates the role of PMP22 in growth arrest, and differentiation may be cell and tissue specific." (PMID 31032403, 2019). "Expression data of EMP1, EMP2, EMP3 and PMP22 were obtained from all tumor samples." (PMID 21159173, 2010). "However, the effect on both Pmp22 and Mbp suggests that perhaps common regulators of Mbp and Pmp22 may be involved during tumor initiation and/or progression." (PMID 31032403, 2019). "Therefore we have computed adjusted survival curves from the multivariable Cox models, which refer to the estimated survival of patients with mean values on tumor size, lymph node involvement, differentiation grade, age and ER expression, and high or low PMP22 expression." (PMID 21159173, 2010). "The age of the patients at diagnosis (median: 58 yrs, range 27 - 89 yrs) and clinical data, including tumor size (pT), differentiation grade (G), nodal status (pN), and histological type of the tumors were analyzed for possible correlations with expression of EMPs and PMP22." (PMID 21159173, 2010). "Similar to PMP22, EMP1 has different mRNA and protein levels in diverse cancers and is involved in tumor cell proliferation, invasion, metastasis, and epithelial-mesenchymal transformation (EMT)." (PMID 36217151, 2022). "EMP3 belongs to the PMP-22/EMP/MP20 family, which is thought to be involved in cell proliferation, cell-cell interactions and function as a tumor suppressor." (PMID 33123464, 2020). "High expression of PMP22 was detected in the Runx1fl/fl;Runx3fl/fl;Nf1fl/fl;DhhCre tumor cells in intracellular structures, including Golgi body, suggesting that RUNX1/3 changes the intracellular trafficking of PMP22." (PMID 31032403, 2019). "We showed that the expression of Pmp22 was increased in Runx1fl/fl;Runx3fl/fl;Nf1fl/fl;DhhCre mouse DRG/tumor spheres and that decreasing Pmp22 expression elevated precursor number, as evidenced by increased sphere numbers." (PMID 31032403, 2019). "Of the remaining genes there is no established relation to pemetrexed or platinum resistance, but PMP22, SRPX are indicators of increased tumour progression and/or aggressivity in other cancers." (PMID 22905093, 2012).
tumor (continued). "The analysis revealed that in the training set, the expression of BANF1, CDK2AP2, DDT, LRIG1, MRPL4, and S100A13 was significantly upregulated in tumor samples, and the expression of EPS8, NUCB2, PAF1, PMP22, RABGAP1L, and USO1 was higher in control samples (p < 0.05)." (PMID 41000388, 2025). "At present, there is no clear evidence of PMP22 acting as an oncogene or as a tumor suppressor gene." (PMID 32174796, 2020). "Besides Pmp22, it is highly possible that other RUNX1/3 targets, such as SDC4, ERN1, and/or MBP, might be involved in tumor formation." (PMID 31032403, 2019).
cancer (21 papers, 2010 to 2025). A tumor composed of atypical neoplastic, often pleomorphic cells that invade other tissues. "Patients with higher than median PMP22 gene expression had a 3.47 times higher risk to die of cancer than patients with lower than median PMP22 expression." (PMID 21159173, 2010). "However, multivariable Cox regression revealed that patients with higher than median PMP22 gene expression have a 3.47 times higher risk to die of cancer compared to patients with equal values on clinical covariables but lower PMP22 expression." (PMID 21159173, 2010). "Moreover, PMP22 mutations can induce neurodegenerative diseases, and the abnormal expression of EMPs might be related to cancer progression." (PMID 36217151, 2022). "Among these clusters, MPZ+ mSCs (cluster 0), PMP22+ mSCs (cluster 1), and SCPs (cluster 4) were predominantly located in cancer-adjacent tissues." (PMID 40148311, 2025). "Herein, we mainly summarized the structure, mutation, and modification sites of PMP22, EMP1, EMP2, and EMP3, as well as the diseases related to these proteins, especially cancer types." (PMID 36217151, 2022). "PMP22 mRNA is also higher in pancreatic ductal adenocarcinoma than in normal pancreatic tissue, suggesting that it is involved in the early development of malignant tumors." (PMID 36217151, 2022). "The PMP22 protein regulates cell growth cycle, cell adhesion, and apoptosis, and is irregularly expressed in various malignant tumors." (PMID 36217151, 2022). "Collectively, these findings manifest that compartment switching induced by Arid1a depletion modulates the transcription of some cancer-related genes, such as Pmp22, Atg10, Gsc, Rnf125, and Cdh5, which have been known to be involved in tumorigenesis." (PMID 34689165, 2021). "Recently, more studies have described a role for PMP22 in cell proliferation and tumorigenesis in different cancers." (PMID 32174796, 2020). "Similar to EMPs, the atypical activity of PMP22 is correlated with metastatic progression in certain cancers." (PMID 31652725, 2019). "Moreover, the genes HES6, SHISA2, PMP22, and IL1RL1 are primarily associated with the progression of cancer and diseases." (PMID 39336820, 2024). "However, a recent investigation of the differential gene expression profiles of normal, primary cancer, and metastatic cancer cells showed that PMP22 expression is often reduced." (PMID 36217151, 2022). "However, recent studies have shown that PMP22 is closely related to cell proliferation and tumorigenesis in different cancers." (PMID 32174796, 2020). "However, the relationships of PMP22 expression level to prognosis and the outcome of different cancer types are contradictory." (PMID 26672768, 2016). "However, little is known about the functions of PMP22 in human cancer." (PMID 21159173, 2010). "Hence, PMP22 might have a great value in the clinical treatment and prognosis of malignant tumors." (PMID 36217151, 2022). "In contrast, genes in neural (CDS1 and CHD4) and cancer-related (BTG1, COL6A1, PMP22 and HIF1A) pathways were increased by STAT3-KD, and their expression was reduced by STAT3 expression." (PMID 29774125, 2018).
genetic disorder (5 papers, 2017 to 2025). "HNPP is an autosomal dominantly inherited genetic disease caused by a heterozygous deletion or point mutation of the PMP22 gene in human chromosome 17p12." (PMID 36197172, 2022).
infection (5 papers, 2019 to 2025). The state of being infected such as from the introduction of a foreign agent such as serum, vaccine, antigenic substance or organism. "Meanwhile, EV71 inhibited the expression of miR-29b and promoted the expression of PMP22 in a time-dependent manner at both mRNA and protein levels, with the most significant change at 36 h of infection." (PMID 39636111, 2025). "The q-PCR results and western blot results confirmed a significant decrease in PMP22 mRNA and protein expression after infection with lentiviruses expressing pLV-shPMP22." (PMID 32174796, 2020). "SGC7901 and BGC823 cells were infected with lentiviruses expressing pLV-PMP22, and the q-PCR results confirmed significantly increased expression of PMP22 mRNA after infection with the PMP22-expressing virus." (PMID 32174796, 2020). "The western blot results showed that the protein level of PMP22 also significantly increased after infection with the PMP22-expressing virus." (PMID 32174796, 2020). "In addition, EV71 inhibited the expression of miR-29b and promoted the expression of PMP22 in a time-dependent manner, with the most significant change at 36 h of infection." (PMID 39636111, 2025). "Furthermore, EV71 promoted the expression of PMP22 and inhibited the expression of miR-29b in a time-dependent manner, with the most significant change at 36 h of infection." (PMID 39636111, 2025). "Infection of CMT1A-iPSC-derived Schwann cell precursors with AAV2-hSaCas9-gRNAedit normalized PMP22 mRNA and PMP22 protein expression levels, and also ameliorated increased apoptosis and impaired myelination in CMT1A-iPSC-derived Schwann cells." (PMID 38017287, 2023). "Here we show that infection of CMT1A-iPS cells (iPSCs) with AAV2-hSaCas9-gRNAedit expressing both hSaCas9 and gRNA targeting the tandem repeat sequence decreased PMP22 gene duplication by 20–40%." (PMID 38017287, 2023). "We also examined PMP22 mRNA and protein levels in iPSC-derived Schwann cells before AAV-infection (Day 42) and after co-culture with normal iPSC-derived neurons (Day 47)." (PMID 38017287, 2023). "While from the immunofluorescence detection, the average fluorescence intensity of PMP22 did not have a significant change along with the prolonged infection time." (PMID 39636111, 2025). "The recovery of the PMP22 levels was not due to the decrease of Schwann cell numbers after infection of AAV2-hSaCas9-gRNAedit." (PMID 38017287, 2023). "Challenges to this gene therapy modality include the need to remove only one copy of the PMP22 gene without disrupting the second copy, and also the efficiencies of infection and genome editing in adult Schwann cells, which produce the myelin sheath of peripheral nerves." (PMID 38017287, 2023).